ALB (albumin)
Diseases named in the same sentence as ALB in open-access papers (continued):
Sharing a sentence is not in itself a finding about the gene and the disease.
infection (continued). "Factorial ANOVA with two independent factors showed a statistically significant effect of time (p = 0.044) and infection (p = 0.002) for albumin." (PMID 27608504, 2016). "For albumin and total protein concentrations, further analyses of the effect of infection showed that these concentrations were significantly lower in infected rams compared to control animals (p < 0.05)." (PMID 27608504, 2016). "The decrease in caseins, β-lactoglobulin and α-lactalbumin and increase in albumin, LF and IgG following infection of the mammary are well known but here the timing of the responses has been identified." (PMID 27412456, 2016). "The total serum protein and albumin in the infection model group was reduced relative to controls, whereas it increased for the middle-dose FBTE group." (PMID 26140539, 2015). "To study clinical outcomes associated to blood NGAL levels, we examined marked changes in serum albumin levels and occurrence of severe infection, but we had to refrain from multifactor adjustments because of little event numbers." (PMID 26161663, 2015). "Their correlation to laboratory findings and morbidity (as development of severe infection or serum albumin reduction) was investigated using linear regression analysis and χ2 test." (PMID 26161663, 2015). "The serum albumin concentration is influenced by not only the nutritional status, but also by many other factors, such as damage to hepatocytes, infection, inflammation, dehydration or fluid retention status, etc.." (PMID 26147805, 2015). "To further establish the effect of the T2SS on cell retraction, we analyzed endothelial cell monolayer integrity during infection in a permeability assay using Transwell plates and albumin-TRITC as a tracer." (PMID 24626230, 2014). "As 90-99% of indomethacin is bound to albumin in the bloodstream, reduced albumin levels lead to an increased concentration of free indomethacin, and thus an even worse antibacterial activity during infection." (PMID 25001579, 2014). "In patients with intestinal failure on HPN the occurrence of low grade fewer, night sweats, declining performance status, low albumin and sometimes increased bilirubin usually prompts the diagnosis of a line related infection." (PMID 24597572, 2014). "In the first 8 h, the serum albumin level was significantly lower in the VC group than in the BC group, which was probably due to a reduction in the hepatocytes’ ability to synthesize albumin following infection with DHV-1." (PMID 25244948, 2014). "Significant change was observed after 7 days of infection, particularly an increase in the density of approximately 66 kDa protein which is thought to be albumin." (PMID 24884439, 2014). "The 3%NI animals showed reduced levels of albumin and globulin (p<0.001), but infection in the malnourished animals (3%INF) promoted a significant increase in globulins (p = 0.002)." (PMID 24586759, 2014). "Administration of icariin or p-icariin groups increased the albumin level compared with the VC group at 54 h after infection, but the levels in both groups were still lower than those in the BC group." (PMID 25244948, 2014). "Clinical factors including days for first fecal passage, dose of postoperative albumin infusion, difference in serum albumin between pre- and postoperation, incidence of postoperative infection, and use of total parenteral nutrition were compared." (PMID 24400032, 2014). "Mean urine albumin values and relationship with parasitological, immunological and proxy marker (microhaematuria) of infection with S." (PMID 24690282, 2014). "Lower level of albumin is bound to weaken the patient's resistance, resulting in slow wound healing and fragile resistance to secondary infection." (PMID 24671050, 2014). "Here, we analyzed the transcriptional response of C. albicans to nitrogen starvation and feeding with the infection-relevant nitrogen sources arginine and bovine serum albumin (BSA), representing amino acids and proteins, respectively." (PMID 24651113, 2014).
infection (continued). "Similarly, low albumin may be a sign of a protein deficient diet or infection." (PMID 24621513, 2014). "As a negative acute phase reactant that is affected by inflammation, albumin typically correlates inversely with infection, trauma, surgery, burns, or oedema." (PMID 24722524, 2014). "Pregnancy, infection and an abnormal serum albumin concentration can affect IMA levels and these potentially confounding factors were exclusion criteria in our study." (PMID 24223946, 2013). "In cirrhotic patients with any infection, there was a significant reduction in mortality (OR 0.46 95%, CI 0.25–0.86) and renal impairment (OR 0.34 95%, CI 0.15–0.75) when albumin was used." (PMID 24222902, 2013). "For DFU patients, the factors affecting outcome include Wagner grades, BMI, serum albumin and, more importantly, infection and nutritional status; the affect of nutritional status is similar in other diseases." (PMID 23251271, 2013). "In cases of cirrhotic patients with infections, death and renal impairment can be reduced with the use of albumin." (PMID 24222902, 2013). "As the Wagner grade of the ulcer increased: the BMI and serum albumin, hemoglobin and total cholesterol levels decreased; the urine protein leakage, severity of infection and percentages of SGA grades B and C increased; and nutritional status deteriorated." (PMID 23251271, 2013). "Low serum albumin and globulin concentrations suggest chronic damage to the liver as a result of infection." (PMID 23861717, 2013). "Our results suggest that albumin has a value in the treatment of cirrhotic patients in the contexts of large volume paracentesis and infections." (PMID 24222902, 2013). "Among DK patients, the infection subgroup had significantly lower levels of albumin and ALT (P = 0.016 and P = 0.001, resp)." (PMID 24282823, 2013). "Diaphragm weakness was correlated with the presence of infection, blood urea nitrogen, albumin, and glucose levels." (PMID 23786764, 2013). "We first investigated the overall lung permeability in infected and uninfected Ifnar1+/+ and Ifnar1−/− mice by i.v. injection of FITC-labelled albumin, followed by analysis of FITC-albumin leakage into the alveolar space 16 hours after infection." (PMID 24244159, 2013). "In accordance with the transcriptional profiling data, functional studies demonstrated that with prolonged infection, cell proliferation increases and lung vascular permeability to albumin decreases." (PMID 23936388, 2013). "The serum albumin level was negatively correlated with the hs-CRP level in these patients, implying that the extent of the decline in the serum albumin level reflects the progress of the sub-clinical inflammation and/or infection." (PMID 24007461, 2013). "The status of the BBB permeability was monitored post-infection every single day by quantifying the albumin and total IgG in the CSF using quantitative ELISA." (PMID 22734518, 2012). "Monkeys further demonstrated a significant infection-related 25.8% decrease in mean plasma albumin concentration, from 35.3±1.9 [CI = 30.4–40.3] g/l at baseline to 26.2±4.2 [95% CI = 15.4–37.0, p = 0.02] g/l at 27 DPI." (PMID 22848769, 2012). "Because most agents used for CED are stored and delivered in solutions containing albumin we first investigated if the albumin concentration would influence infection efficiency." (PMID 22022354, 2011). "A more rapid and cost-effective assay was employed to specifically evaluate serum albumin concentration during the course of PICV infection." (PMID 20846417, 2010). "Previously, evidence of decreased albumin levels in VHF hamster models based on infection with the related Pirital arenavirus and YFV has been reported." (PMID 20846417, 2010). "In parallel to serum albumin, apoliproteins, the major lipid and cholesterol transporters were reduced following infection." (PMID 20602791, 2010).
infection (continued). "Reductions in biologically active albumin mRNA and increased type I procollagen mRNA were observed in the liver of S. mansoni infected mice 6 weeks post-infection." (PMID 20824219, 2010). "Another plasma protein, serum albumin, was also down regulated following infection, although again, only significantly so for the ASL group." (PMID 20602791, 2010). "Clinically relevant factors significantly associated with cycle 1 FN were older age, increasing planned cyclophosphamide dose, a history of previous chemotherapy, a history of recent infection, and low baseline albumin (<35 g/l)." (PMID 19055662, 2009). "Patient and baseline characteristics of older age and low baseline albumin were predictive of cycle 1 FN, as were a clinical history of previous chemotherapy or recent infection." (PMID 19055662, 2009). "NNIS > 1 (p = 0.01) and low preoperative albumin (p = 0.02) significantly correlated with infection." (PMID 17505683, 2007). "Our data suggest that the NNIS index and preoperative albumin level are important predictive factors for perioperative infection." (PMID 17505683, 2007). "The NNIS score and the evolution of serum IL-6 and various acute-phase proteins (C-reactive protein [CRP], albumin, prealbumin and transferrin) were correlated with postoperative infections and length of hospital stay (LOS)." (PMID 17505683, 2007). "The albumin level diminished over time (p < 0.01), with a significantly greater decrease in patients with infections than in others (p = 0.04)." (PMID 17505683, 2007). "Infection was approximately nine times more frequent in patients with preoperative albumin below 3 g/dl (OR = 9.10; 95% CI: 1.38-59.62; p = 0.02)." (PMID 17505683, 2007). "There was a 48% incidence of infection in those admitted with a serum albumin of less than 2.6 gms/dL and a 28% incidence in those with an albumin of 2.6 gms/dL or above (p < 0.001)." (PMID 16952310, 2006). "Augmentation of phage infection rate with each round of panning against albumin-depleted G/LCM containing GnSAF bioactivity." (PMID 16185358, 2005). "In addition to mortality, we examined the relationship between albumin levels and key clinical outcomes, including emergency department utilization, hospital admissions, cardiovascular events, and infection-related hospitalizations." (PMID 41517580, 2026). "From a practical standpoint, routinely available markers (CRP, PCT, leukocyte-derived indices, albumin, lactate) are the most immediately actionable when interpreted longitudinally to distinguish expected postoperative inflammation from evolving infection and to support early stratification." (PMID 41598637, 2026). "A decrease in the serum albumin concentration could be due to an acute phase response invoked/generated due to induced infection." (PMID 41568335, 2025). "It has also been suggested that decreased albumin concentration can reduce plasma osmotic pressure, resulting in tissue edema, interstitial fluid leakage, pulmonary congestion, and edema, and promote infection." (PMID 40225039, 2025). "In infection or chronic inflammation, serum albumin levels decrease." (PMID 40313464, 2025). "C-reactive protein and albumin are both acute-phase reactive proteins synthesized by the liver, with C-reactive protein levels increasing and albumin levels typically decreasing during the course of infection or inflammation." (PMID 40303878, 2025). "On the contrary, the ALB level in the infection group was significantly lower (p < 0.01)." (PMID 40125519, 2025). "While these indices have been validated in oncologic and cardiovascular cohorts, their limited utility in acute care likely reflects the variability of CRP and albumin in ED patients, where acute inflammatory conditions such as infection, trauma, and systemic inflammation are common confounders." (PMID 41300867, 2025).
infection (continued). "We also explore the correlations between lactate, albumin, and procalcitonin stratified by infection focus (urinary vs. non-urinary) to determine whether biomarker relationships differ by site of infection." (PMID 41590227, 2025). "However, because ionized calcium can be accessed via arterial or venous sampling or estimated from total calcium and albumin levels, we employed corrected calcium in our cohort to evaluate its predictive value in severe infections." (PMID 41291834, 2025). "For example, serum zinc is affected by stress, inflammation, infection, or albumin concentrations." (PMID 40822595, 2025). "Four days after mock or SARS-CoV-2 infection, there was increased albumin leakage into bronchoalveolar lavage fluid (BALF) synonymous with pulmonary edema in the infection group, while baseline levels were similar between Hif1afl/fl SPCCreER and SPCCreER control mice." (PMID 40526427, 2025). "infections is still a matter of debate, although many physicians are in the habit of infusing ThHSA to restore the physiological concentration of endogenous human serum albumin (HSA)." (PMID 41148665, 2025). "Before nephrectomy, the median number of albumin infusions per month (day/month), the median number of infections and hospitalizations per year, and median hospitalization duration (days) were 20 (IQR: 12–28), 3 (IQR: 2–4), 4 (IQR: 2.25–6), and 13 (IQR: 11–27.6), respectively." (PMID 40266336, 2025). "At the time of CNS diagnosis, the median number of albumin infusions per month (day/month), and the median number of infections, hospitalizations per year, median hospitalization duration (days) were 12 (IQR: 8–24), 2 (IQR: 1–3.5), 4 (IQR: 2–5.75), and 9 (IQR: 2.5–10), respectively." (PMID 40266336, 2025). "Baseline characteristics and clinical outcomes were similar in the two groups, except for the Charlson Comorbidity Score, the leucocyte count, the albumin, the site of infection, and the length of stay, which were significantly different between the two groups." (PMID 41009898, 2025). "Without the albumin, S. aureus can adhere more easily to the surface, increasing the risk of infection." (PMID 40565919, 2025). "Low albumin is associated with frailty in individuals with CKD; older adults also have a higher risk of frailty, which is associated with poor quality of life, risk of hospitalization, infection, CVD events, HD related complications, and mortality." (PMID 40824912, 2025). "Our results are consistent with previous studies, indicating that patients with lower PNI may have inadequate nutrition, poor infection control, and immune imbalance, which can lead to reduced albumin and lymphocyte levels." (PMID 40667438, 2025). "Moreover, in a pediatric HCT study, low pre‐HCT serum albumin levels were associated with an increased need for critical care interventions and 6‐month NRM caused by pulmonary toxicity and infection." (PMID 39866921, 2025). "Mechanistically, albumin is first and foremost a key regulatory factor in infection prognosis." (PMID 41355981, 2025). "Further optimization of the synthesis, functionalization, and delivery mechanisms of albumin-based nanoparticles could expand their applications in combating resistant infections and improving global health outcomes." (PMID 40343307, 2025). "Even if nephrectomy does not alter the overall prognosis, its effectiveness in decreasing the number of albumin infusions required, infections, and hospitalizations may still have significant direct and indirect benefits." (PMID 40266336, 2025). "Indeed, higher concentrations of serum albumin have been described at sites of infection, which activates a glycerol monolaurate suppressive effect on human T cells." (PMID 40277801, 2025). "However, our comprehensive adjustment for albumin infusion and infection sources mitigates major confounding concerns." (PMID 40969605, 2025).
infection (continued). "CRP/ALB ratio levels are a good reflection of microvascular permeability, and there is a certain correlation between the levels and the degree of capillary leakage, which is one of the pathological features of organic infection." (PMID 41019129, 2025). "In a study with 9,001 arthroplasty patients, those with albumin concentration < 3.5 g/dl were more likely to develop deep PJI (adjusted odds ratio 4.69,p < 0.001).36The infection rate in patients with low albumin (7.3%) was significantly higher than in our study (3.3%)." (PMID 40727701, 2025). "Nephrectomy reduces albumin infusions, infections, and hospitalizations, suggesting it may be a beneficial treatment for selected CNS patients with NPHS1 mutations." (PMID 40266336, 2025). "Currently, the application of NLR and CRP/ALB ratio in predicting early infection after open fracture and bone arthroplasty has been investigated, however, they have been relatively less studied in the prediction of postoperative infections in patients with spinal disorders." (PMID 41019129, 2025). "Hypotension, abnormalities in serum electrolytes, albumin, calcium, and phosphate, hypothermia, infection and bleeding, sub-therapeutic antibiotic concentration, arrhythmia, membrane bio incompatibility, and complications due to vascular access are well-recognised complications of RRT." (PMID 40861663, 2025). "Second, the tool itself should be refined and recalibrated by adding age, nutritional/functional markers (e.g., BMI, serum albumin, brief frailty screens) and selected comorbidities to improve discrimination for clinically meaningful infection endpoints, beyond VA-focused items alone." (PMID 41373275, 2025). "Also, infection induced an increase in the levels of albumin in the urine as well as urinary γ-glutamyl transferase (γ-GT) activity, cortical kidney injury molecule-1 (KIM-1) and urinary β2-microglobulin (β2M), markers of renal tubular injury." (PMID 40661967, 2025). "However, they were unable to protect the larvae from infection with S. aureus because components of the larval coelom neutralized the antimicrobial activity; a similar effect was also seen with serum albumin." (PMID 39125595, 2024). "On the other hand, low level of serum albumin increased the odds of infection by 7%." (PMID 38987746, 2024). "Serum albumin levels are traditionally used as indicators of nutritional status and infection." (PMID 39281816, 2024). "Albumin, globulin, and albumin to globulin ratio are helpful in prosthetic joint infection diagnosis, and albumin is a potential marker for deciding reimplantation after infection." (PMID 39493345, 2024). "Furthermore, this study sought to report correlations between low serum albumin and the incidence of organ-space infections." (PMID 38817798, 2024). "Multivariate stepwise regression analysis identified white blood cell count (WBC), lymphocyte to monocyte ratio (MLR), platelet to neutrophil ratio (PNR), red cell distribution width-standard deviation (RDW-SD), and albumin (ALB) as significant predictors of postoperative infection." (PMID 39583098, 2024). "Albumin reflects the patient’s nutritional status, and when nutrition is poor, the body mobilizes proteins and amino acids to convert them into glucose to ensure adequate blood sugar supply during stress or infection." (PMID 39398953, 2024). "Notably, risk factors significantly associated with AKI included elevated MELD score, Child-Pugh-Turcotte stage, infection, SCr, bilirubin levels, and low serum albumin." (PMID 38361702, 2024). "We examined multiple outcomes such as surgery duration in hours, time until bowel function returned post surgery, length of hospital stay in days, anastomotic leak rate, albumin levels to leak rate, post-surgery pain, and surgical site infection (SSI) rate for the two groups." (PMID 39525136, 2024).